VIM (vimentin)
Diseases named in the same sentence as VIM in open-access papers (continued):
Sharing a sentence is not in itself a finding about the gene and the disease.
hepatocellular carcinoma (continued). "Virtually, knockdown of LINC01287 upregulates E-cadherin level and reduces N-cadherin and Vimentin levels in hepatocellular carcinoma cells, indicating that LINC01287 is also involved in the EMT of hepatocellular carcinoma." (PMID 34229645, 2021). "It has been recently shown that myricetin inhibited EMT in hepatocellular cancer cell line MHCC97H by increasing E-cadherin and decreasing N-cadherin and vimentin mRNA expression levels." (PMID 35069190, 2021). "Together, these findings suggested that vimentin was involved in the proliferation and migration mediated by HBX in hepatoma cells." (PMID 33722250, 2021). "Furthermore, HBX could reduce the ubiquitination level of vimentin in hepatoma cells." (PMID 33722250, 2021). "Compared to control cells, the increased expression of vimentin and β-catenin, and decreased E-cadherin were observed in HBX-positive hepatoma cells." (PMID 33722250, 2021). "As expected, the results showed that the stability level of vimentin was decreased, and the ubiquitination level of vimentin was enhanced, when HBX-positive hepatoma cells were incubated with LASP1 shRNA." (PMID 33722250, 2021). "Functionally, vimentin was contributed to the EMT, proliferation, and migration of hepatoma cells mediated by HBX." (PMID 33722250, 2021). "Trastuzumab with the high concentrations suppressed proliferation of HER2‐positive hepatoma cells (P < 0.05); in the coculture model to induce EMT of JM1 cells, HER2 expression increased with downregulated E‐cadherin and upregulated Vimentin." (PMID 30714677, 2019). "HBx-transfected hepatoma cells incubated with CM from HUVECs also expressed mesenchymal genes including Thy1, CDH2, TGFβR1, VIM, and CD133." (PMID 31069171, 2019). "SNAIL can enhance the expression of mesenchymal genes, like vimentin in ovarian cancer and matrix degradation enzyme MMP9 in hepatocellular carcinoma (HCC)." (PMID 30781524, 2019). "Furthermore, knockdown of this lncRNA in Hepatocellular Carcinoma (HCC) cells results in reduced vimentin and N-caherin expression with restoration of E-cadherin expression, further supporting a role for this lncRNA in the regulation of EMT." (PMID 29701689, 2018). "The galactosylated liposomal doxorubicin vehicle (Gal-DOX-L) and gal-doxorubicin/vimentin siRNA liposome (Gal-DOX/siRNA-L) had the correct size (<100 nm and <140 nm, each), delivered DOX and siRNA into hepatoma cells showing dose-dependent efficacy." (PMID 28335269, 2016). "For example, in hepatocellular carcinoma, miR-17-5p reduced the translation of PTEN mRNA, while miR-17-3p directly targeted vimentin mRNA." (PMID 26629823, 2015). "miR-30 family also inhibits cell migration, invasiveness, and metastasis in vitro in other tumors, such as lung, breast, and hepatocellular cancer, by targeting SNAI1 and Vimentin." (PMID 25409297, 2014). "We found decreased E-cadherin and increased vimentin expression in cells with overexpressing PDGFRα, indicating that PDGFRα promoted epithelial-mesenchymal transition (EMT) of hepatoma cells." (PMID 25333264, 2014). "Additionally, in hepatocellular carcinoma cell lines, SIRT5 directly interacts with vimentin and catalyzes its deacetylation at lysine 120, a modification that attenuates vimentin function and subsequently suppresses cell migration." (PMID 41304967, 2025). "Moreover, in hepatocellular carcinoma cells, overexpression of STAT3 significantly reduced the expression of cell adhesion molecules but enhanced the expression of N-cadherin and Vimentin." (PMID 39195486, 2024). "It was uncovered that the alternative activation of macrophages induced by IL-25 promoted the migration, invasion and tumorigenesis of hepatoma cells, increased the expression of vimentin, Snail and phospho-ERK, and decreased the expression of E-cadherin in hepatoma cells." (PMID 38818476, 2024). "Both hepatoma cell lines expressed vimentin and α-smooth muscle actin (α SMA) and HLE was negative for cytokeratin." (PMID 37762298, 2023).
hepatocellular carcinoma (continued). "We found that JPHYD could inhibit the proliferation, invasion, and migration of hepatocellular carcinoma cells and JPHYD decreased the level of N-cadherin, Snail, Vimentin, Smad3, and Zeb1 and increased E-cadherin and Smad7 proteins." (PMID 35518787, 2022). "Overexpression of non-acetylated vimentin attenuates the migration activity of hepatocellular carcinoma cells." (PMID 35163593, 2022). "Annexin-A3 is part of a family of calcium-binding proteins known to promote granule fusion in PMNs and to increase neutrophil migration in hepatocellular carcinoma, while vimentin is an intermediate filament found in non-muscle cells." (PMID 34966382, 2021). "Our published studies showed that HBX promotes the proliferation and migration of hepatoma cells, we next measured whether HBX could facilitate cellular proliferation and migration via vimentin." (PMID 33722250, 2021). "Taken together, these results suggested that HBX could interact with vimentin and LASP1, and protect vimentin from ubiquitination and degradation via LASP1 in hepatoma cells." (PMID 33722250, 2021). "In the present study, we demonstrated that HBX could facilitate vimentin expression via LASP1 to promote EMT, proliferation, and migration of hepatoma cells." (PMID 33722250, 2021). "The suppression of vimentin has no significant role in LASP1 expression in HBX-positive hepatoma cells." (PMID 33722250, 2021). "We were interested in investigating whether HBX could promote EMT via vimentin, and the effect of vimentin on the expressions of EMT markers, including E-cadherin and β-catenin, in hepatoma cells." (PMID 33722250, 2021). "Likewise, the fluorescence signals of vimentin and N-cadherin were declined in LINC01488-overexpressing hepatoma cells." (PMID 32575745, 2020). "Moreover, morusin treatment also suppresses the metastatic capacity of the human hepatoma SK-Hep1 cell line, which may be biochemically associated with inhibition of STAT3 and NF-κB followed by the reduction of the expression of metastatic markers, such as vimentin, α2- and β1-integrins." (PMID 32906784, 2020). "Moreover, mRNA and protein levels of vimentin, N-cadherin, and MMP-9 were significantly increased in LINC01488 knockdown hepatoma cells, compared with cell lines transfected with control shRNA." (PMID 32575745, 2020). "Similarly, the fluorescence signals of vimentin and N-cadherin were stronger in LINC01488 knockdown hepatoma cells than in control shRNA HCC cells by immunofluorescence analysis." (PMID 32575745, 2020). "In addition, our results are consistent with the findings in hepatocellular carcinoma, and we found that miR‐874 suppressed the EMT by downregulating E‐cadherin and upregulating N‐cadherin and Vimentin expression in A549 cells." (PMID 32301290, 2020). "Other potent antioxidants, such as resveratrol and curcumin, increased the expression of epithelial phenotype marker E-cadherin and reduced the expression of mesenchymal phenotype markers, vimentin and fibronectin, thus suppressing TGF-β1-induced EMT in lung and hepatoma cell lines." (PMID 30984333, 2019). "According to recent reports, ectopic expression of RUNX3 promoted E-cadherin expression, but had a negative effect on Vimentin in hepatocellular carcinoma cells." (PMID 28977878, 2017). "Ectopic expression of RUNX3 reportedly promoted E-cadherin expression, but had a negative effect on vimentin in hepatocellular carcinoma cells." (PMID 29254144, 2017). "Vimentin expression is increased in HCV-infected human hepatoma cells compared with parental cells but not in patients without chronic hepatitis." (PMID 26544179, 2015). "Both cell lines studied (liver carcinoma-derived PLC and the intestine carcinoma-derived CaCo-2 cells) express the IF proteins cytokeratins 8 and 18 and due to culturing conditions, also some vimentin as an additional IF protein." (PMID 23704888, 2013).
hepatocellular carcinoma (continued). "The results were further validated by RT-PCR, western blot, flow cytometry or immunofluorescent staining which revealed that prominin-1, annexin A1, annexin A3, transgelin, creatine kinase B, vimentin, and EpCAM were indeed highly expressed in the CD133-positive hepatoma cells." (PMID 23170877, 2012). "In hepatocellular carcinoma (HCC), LPS promotes cell survival, proliferation, invasion, and production of pro-inflammatory mediators, including TNF-α, iNOS, IL-1β, IL-6, CCL-2, CCL-22, vimentin, and epidermal growth factor receptor (EGFR), through the induction of TLR4 signaling." (PMID 40444051, 2025). "Similarly, in hepatocellular carcinoma (HCC), hypoxia-induced integrin β4 (ITGB4) activates the TGF-β/Smad pathway, promoting lactate secretion that transforms hepatic stellate cells (HSCs) into CAFs marked by elevated α-SMA and vimentin expression." (PMID 40565047, 2025). "Furthermore, in hepatocellular carcinoma (HCC), ZKSCAN3 facilitates epithelial-mesenchymal transition (EMT), as evidenced by changes in the expression patterns of EMT markers, including decreased E-cadherin and increased N-cadherin and vimentin levels." (PMID 39519085, 2024). "Moreover, the western blot experiments verified that CEBPA-DT overexpression repressed the protein expression of E-cadherin and induced the expressions of N-cadherin, Vimentin, Snail and DDR2 in hepatoma cells, while CEBPA-DT down-regulation showed contrary results." (PMID 36471363, 2022). "In hepatoma, Twist1 can promote vimentin expression, and it has been verified that Twist1 is combined with a circular RNA, the promoter region of CUL2 (Cullin-2), and promotes the mRNA of vimentin by adsorbing the microRNA targeting vimentin degradation, resulting in EET." (PMID 33397409, 2021). "We investigated whether LASP1 could enhance vimentin expression via the signal pathways and the results showed that over-expressed LASP1 could promote the activation of PI3-K, ERK, STAT3 pathways in hepatoma cells." (PMID 33722250, 2021). "Most importantly, vimentin undergoes various functionally important PTMs, including acetylation, and one sirtuin family member, SIRT5, was found to physically interact with and deacetylate vimentin at K120 and thus influence the EMT process in hepatocellular carcinoma cells." (PMID 34605151, 2021). "In hepatocellular carcinoma (HCC) cells, TRIP13 knockdown increases levels of the epithelial marker, E‐cadherin, and decreases the mesenchymal markers, vimentin, and snail." (PMID 33037736, 2020). "However, our data showed that that LINC01488 positively regulates miR-124-3p and miR-138-5p to reduce vimentin expression in hepatoma cells, indicating that lincRNAs not only act as miRNA sponges but also regulators to modify target mRNA levels." (PMID 32575745, 2020). "SIRT1 is upregulated in the majority of hepatocellular carcinomas (HCCs) and enhances the invasive and metastatic potential of HCC by activating EMT markers, such as SNAIL, TWIST, and VIMENTIN, and inhibiting E-cadherin." (PMID 30761005, 2019). "Hepatoma cell lines that were classified as epithelial due to their E-cadherin expression were sensitive to EGFR inhibitors, whereas hepatoma cell lines classified as mesenchymal (vimentin-positive) were resistant to EGFR inhibitors and displayed increased Akt and STAT3 phosphorylation." (PMID 26729094, 2015). "Analysis of human hepatocellular carcinoma (HCC) tissues in relation to patient overall survival showed poorer prognosis for those having tumours expressing MORs and vimentin or MOR with concomitant absence of E-cadherins." (PMID 39861181, 2025). "Furthermore, the increased expression of mesenchymal markers vimentin and CD90 has been detected in sphere-forming cells of human primary hepatocellular carcinoma (HCC) and human HCC cell lines." (PMID 36474162, 2022).
hepatocellular carcinoma (continued). "However, whether vimentin participates in the dysfunction of hepatoma cells mediated HBX, and the molecular mechanisms associated with vimentin expression mediated by HBX are not clear." (PMID 33722250, 2021). "One study indicated that low dose of SHK (4 μM) (around 1.33 μg/mL) did not influence the survival of hepatocellular carcinoma cells but inhibited the migratory ability through downregulation of MMP-2 and -9 and vimentin expressions." (PMID 25737737, 2015). "When cells were treated with IL-7R shRNA, the expression of vimentin and β-catenin increased, while E-cadherin decreased significantly, suggesting that IL-7R had a negative role on EMT in hepatoma cells, and that HBX-mediated EMT in hepatoma cells was independent of IL-7R." (PMID 27821177, 2016).
cervical carcinoma (113 papers, 2006 to 2026). A carcinoma arising from either the exocervical squamous epithelium or the endocervical glandular epithelium. "Collectively, the currently available data suggests that cervical cancers with unclear tumor borders are associated with higher vimentin expression, lymph node metastasis rate, incidence of LVSI, and recurrence rate versus tumors with clear borders." (PMID 37717112, 2023). "In cervical cancer, high expression of vimentin has been associated with lymph node metastasis, lymphovascular space invasion (LVSI), and prognosis." (PMID 37717112, 2023). "Upregulation of Vimentin and N-cadherin were also detected associated with the interaction of Par-4 in cervical cancer during transforming growth factor (TGF)-β-induced EMT." (PMID 35628455, 2022). "Previous study has also demonstrated that EMT is implicated in poor cervical cancer prognoses through inactivation of E-cadherin and activation of vimentin." (PMID 35406599, 2022). "A previous study has shown that EMT is a primary process that involves increased cervical cancer metastasis with loss of epithelial markers, such as E-cadherin, and a gain of mesenchymal markers, such as vimentin." (PMID 34210327, 2021). "Here, we determined the prognostic significance of L1CAM in cervical cancer and its association with vimentin expression on tumor cells, indicative of EMT." (PMID 29152102, 2017). "Decreased gelsolin expression caused decreased cell migration, MMP2 expression, vimentin, and upregulated E-cadherin expression in cervical cancer cells." (PMID 26356073, 2015). "Notably, in human cervical cancer specimens with PNI, we found close associations between GFAP+ or Vimentin+ SCs and cervical cancer cells." (PMID 37830980, 2023). "EMT is a vital process contributing to cervical cancer progression, invasion and metastasis and characterized by the loss of epithelial markers, such as E-cadherin, and the gain of mesenchymal markers, such as N-cadherin and vimentin." (PMID 37845756, 2023). "Although Ki-67 expression has not been found to be associated with patient’s general survival in studies conducted by us and other groups, we found that Vimentin expression was significantly associated with a decreased proliferation rate of cervical cancer as measured by the Ki-67 labeling index." (PMID 28912668, 2017). "Interestingly, we found out that Vimentin protein expression is strongly associated with the onset age, lymph node metastasis, lymphatic invasion, Ki67 staining, recurrence, and survival in cervical cancer patients." (PMID 28912668, 2017). "L1CAM might be a promising new prognostic marker for locoregional recurrences in cervical cancer, and its association with vimentin expression suggests that L1CAM might affect tumor aggressiveness, possibly through EMT." (PMID 29152102, 2017). "Consequently, we firstly examined the association between TRIM62 and EMT markers (α-Catenin and Vimentin) expression in human cervical cancer by IHC." (PMID 27793172, 2016). "To determine whether alterations in the EMT is responsible for the promotion of invasion and migration caused by RSU1P2 in cervical carcinoma cells, we performed western blot assays to detect the protein levels of the epithelial marker E-cadherin and the mesenchymal markers vimentin and ICAM-1." (PMID 27487126, 2017). "To explore the expression patterns of EMT markers in cervical cancer, we examined a series of classical proteins, including E-cadherin, vimentin, and snail." (PMID 41496085, 2026). "To assess the universality of hypoxia‐induced vimentin reorganization, we extended these observations to HeLa cells, a widely utilized cervical cancer cell line and canonical model in cell biology research." (PMID 40884268, 2025). "For these reasons, this study evaluated the effect of supernatants from cervical cancer cell lines (HeLa and SiHa) in the expression of vimentin, S100A4, αSMA, FAP, and MMP9 markers in an in vitro MSC-CAF model." (PMID 38606999, 2024).